DPP4 (dipeptidyl peptidase 4)
Diseases named in the same sentence as DPP4 in open-access papers (continued):
Sharing a sentence is not in itself a finding about the gene and the disease.
diabetic nephropathy (continued). "Other DPP-4 inhibitors have also demonstrated renoprotective effects in animal models of diabetic nephropathy, as reviewed elsewhere." (PMID 29491123, 2018). "Previous clinical studies have shown a beneficial effect of DPP-4 inhibitors in diabetic nephropathy." (PMID 28761658, 2017). "The knowledge that DPP-4 has the highest expression levels in the kidneys of mammals, which is additionally upregulated in DN, indicates that DPP-4 inhibition by sitagliptin is a plausible therapeutic target for management of diabetic nephropathy." (PMID 29098166, 2017). "A similar condition (reduced renal DPP-4 activity despite enhanced protein levels) has been reported in a rat model of diabetic nephropathy." (PMID 28118775, 2017). "Antihyperglycemic and renoprotective effects make DPP-4 inhibitors a useful addition to DM treatments, suppressing the onset and progression of diabetic nephropathy; however, further prospective studies are necessary." (PMID 29187821, 2017). "Previous studies have reported that a DPP-4 inhibitor prevents exacerbation of diabetic nephropathy through anti-inflammatory effects in a rat model of type 1 diabetes." (PMID 27513960, 2016). "To explore these issues, we investigated the effects of a DPP-4 inhibitor, gemigliptin, on diabetic nephropathy and cardiomyopathy." (PMID 26959365, 2016). "In diabetic nephropathy, the miRNA-29 family protects the kidney from fibrotic damage, and the DPP-4 inhibitor linagliptin has been shown to inhibit TGF-β-induced endothelial to mesenchymal transition (EndMT) by restoring the miRNA-29s’ levels." (PMID 27153060, 2016). "In this review, we focus on the possible mechanisms by which DPP-4 inhibitors combat diabetic nephropathy, especially about kidney fibrosis." (PMID 26877767, 2016). "In summary, we propose novel mechanistic data that adds to the existing body of knowledge that DPP4 inhibition with linagliptin can inhibit the TGFß1 related fibrotic pathway in diabetic nephropathy." (PMID 26509887, 2015). "We highlight the novel pleiotropic effects of DPP4 that make it an attractive additional target to combat the fibrotic and inflammatory pathways in diabetic kidney disease and also discuss the current literature on the cardiovascular safety profile of DPP4inh." (PMID 26379674, 2015). "There is also experimental evidence to suggest that DPP4 is involved in the advanced glycation end product – receptor axis, which is highly relevant in diabetic kidney disease." (PMID 26379674, 2015). "In conclusion, DPP-4 inhibitor, a first-line medication for diabetic nephropathy, reduces the impact of IS through the anti-apoptotic and anti-fibrotic properties." (PMID 24755682, 2014). "Previous studies have suggested that therapeutic intervention with a DPP-4 inhibitor is effective in postponing the development of neuropathy, cardiovascular disease, and diabetic nephropathy." (PMID 24972137, 2014). "Ongoing prospective studies focused on the nephroprotective effects of DPP-4 inhibitors will further clarify its possible role in the prevention/attenuation of diabetic kidney disease beyond its glucose lowering properties." (PMID 24089613, 2013). "One of the interesting possibilities that have emerged from experimental studies is the protective effect of DPP-4 inhibitors on the diabetic kidney disease." (PMID 24089613, 2013). "One of the recently emerged interesting features of dipeptidyl peptidase-4 (DPP-4) inhibitors is its possible protective effect on the diabetic kidney disease." (PMID 24089613, 2013). "Evidence from investigations with DPP-4 inhibitors in diabetic eNOS knockout mice, a model of diabetic nephropathy, suggests the potential of DPP-4 inhibitors to reduce albumin excretion." (PMID 23785355, 2013). "We will discuss potential mechanism of these effects, the differences between various DPP-4 inhibitors, and future perspectives of its use in patients with diabetic kidney disease." (PMID 24089613, 2013).
diabetic nephropathy (continued). "The present review will highlight the most recent findings in the literature about these pleiotropic effects and the potential mechanisms underlying these benefits, with a specific focus on the potential effectiveness of DPP-4 inhibitors in coronavirus disease-19 and diabetic kidney disease." (PMID 39526061, 2024). "Moreover, DPP-4 inhibitors exert reno-protective effects in diabetic nephropathy through glucose-dependent and glucose-independent mechanisms." (PMID 39271520, 2024). "Upregulation of DPP-4 in diabetic nephropathy makes it a promising potential therapeutic target." (PMID 39271520, 2024). "Recent reports have shown the benefits of giving DPP4 inhibitors to diabetic nephropathy patients." (PMID 35956932, 2022). "It should be determined whether DPP-4 inhibitors are useful in patients with non-diabetic kidney disease." (PMID 33923115, 2021). "Furthermore, to test the contribution of DPP-4 in the diabetic nephropathy, we measured the DPP-4 activity in the plasma and the kidney." (PMID 32085655, 2020). "DPP4 inhibitors may exert beneficial effects on diabetic nephropathy (DN) independently of glycemic control; however, the mechanisms underlying are not fully understood." (PMID 31905169, 2020). "First, although the experimental data are conflicting, it is possible that potentiation of SDF-1 by DPP-4 inhibitors may enhance the inflammatory and proliferative responses to kidney injury and may thereby aggravate the course of diabetic nephropathy." (PMID 29310647, 2018). "The kidneys contain the highest levels of DPP-4, which is increased in diabetic nephropathy." (PMID 29491123, 2018). "Dipeptidyl peptidase-4 (DPP-4) inhibitors may have protective effects on diabetic kidney disease (DKD) via specific antioxidant pathways." (PMID 29979777, 2018). "Nevertheless, many of the large-scale cardiovascular trials have reported the effects of DPP-4 inhibitors on aspects of diabetic nephropathy, specifically changes in urinary protein excretion, in glomerular function over time, and in the risk of progression to end-stage renal disease." (PMID 29310647, 2018). "Based on these studies, it seems plausible that DPP-4 plays a pathological role in diabetic nephropathy, although reverse causation cannot be ruled out." (PMID 29491123, 2018). "Among them F1 (rich in quercetin glucosides and pentacyclic triterpene ester) and F2 (containing large amounts of carbohydrates and polysaccharides) were found to be especially effective in attenuating DPP-4 signaling, and to have the potential to counter diabetic nephropathy." (PMID 28715446, 2017). "The renoprotective effect of DPP-4 inhibitors in diabetic nephropathy may be exerted through an increase in active GLP-1 or through the inhibition of DPP-4 itself." (PMID 28761658, 2017). "Finally, Panchapakesan and Pollock (Australia) summarize potential renoprotective effects of DPP4 inhibitors in diabetic kidney disease and also discuss the cardiovascular safety profile of DPP4 inhibitors." (PMID 26925063, 2016). "In this review, we discuss the dipeptidyl peptidase 4 (DPP4) inhibitors (DPP4inh), which are glucose-lowering agents used clinically and their role in diabetic kidney disease with specific focus on renoprotection and surrogate markers of cardiovascular disease." (PMID 26379674, 2015). "Hence we would propose that effective treatments to limit diabetic nephropathy necessarily involve targeting multiple pathophysiological pathways, which include inhibition of membrane bound DPP4." (PMID 26509887, 2015). "Additionally, research groups are also working on fluorescent probes such as GP-DCMNH2 for the early detection of DPP4 as a biomarker for diabetic nephropathy, and the early evidence has shown stronger fluorescence signals in the kidneys and blood of mice with diabetic nephropathy." (PMID 35956932, 2022).
diabetic nephropathy (continued). "Moreover, in an experimental model, DPP-4 inhibitors, especially gemigliptin, substantially decreased albuminuria and renal fibrosis in mice with unilateral ureteral obstruction and attenuated podocyte injury in mice with diabetic nephropathy." (PMID 34697593, 2021). "Dipeptidyl peptidase 4 inhibitors and angiotensin II receptor blockers attenuate chronic kidney disease progression in experimental diabetic and non-diabetic nephropathy in a blood pressure and glucose independent manner, but the exact molecular mechanisms remain unclear." (PMID 32099009, 2020). "Despite the many studies described here showing renoprotective effects of linagliptin and other DPP-4 inhibitors in animal models of diabetic nephropathy and non-diabetic kidney disease, as yet there is little clinical data to support the hypothesis that these drugs have pleiotropic renal benefits." (PMID 29491123, 2018). "Therefore, we excluded five patients who received additional treatment with anagliptin, and analyzed 20 subjects who were switched to anagliptin from other DPP-4 inhibitors for evaluating the effect of anagliptin on glycemic control, lipid data and diabetic nephropathy in this study." (PMID 28761658, 2017). "In addition, DPP4 activity is regulated through glycosylation in diabetic nephropathy." (PMID 27213360, 2016). "DPP-4 inhibitors may ameliorate diabetic nephropathy and reduce the overproduction of TGF-β1." (PMID 26877767, 2016). "A study of CRP-driven diabetic nephropathy showed that CRP triggers the aggregation of DPP4 and CD32b at the protein level to form DPP4/CD32b/NF-κB signaling." (PMID 37893085, 2023). "miR-29 clusters target the profibrotic molecule DPP-4, and its inhibition elevates the miR-29 level; therefore, DPP-4 inhibitors are potential leads for the treatment of diabetic nephropathy." (PMID 34199672, 2021). "In various animal models of non-diabetic kidney disease, metformin, GLP-1R agonists, DPP-4 inhibitors, and SGLT-2 inhibitors were favorable to kidney morphology and function." (PMID 33923115, 2021). "Thus, both DPP-4 pathway could develop diabetic nephropathy." (PMID 32238837, 2020). "Upregulation of renal DPP4 has been demonstrated in both experimental CKD models and human glomerular disease and has been correlated to glomerulosclerosis in diabetic nephropathy." (PMID 30774748, 2019). "In recent years, multiple actions of dipeptidyl peptidase 4 (DPP-4) inhibitors and glucagon-like peptide-1 receptor (GLP-1R) agonists have been well defined in animal models of diabetic kidney disease (DKD)." (PMID 29607314, 2018). "Likewise, limited evidence exists recommending the clinical use of dipeptidyl peptidase-4 (DPP-4) inhibitors and endothelin receptor antagonists in the treatment of hypertensive nephropathy, although there is good evidence in diabetic kidney disease." (PMID 40806733, 2025). "In conclusion, the DPP-4 inhibitor sitagliptin in a dose of 50 mg orally per day for 3 months was a safe add-on therapy to the AHCL system for adolescents with type 1 diabetes and diabetic nephropathy." (PMID 39271520, 2024). "Considering the paucity of new agents to treat kidney disease and the minimal adverse effects of metformin, GLP-1R agonists, DPP-4 inhibitors, and SGLT-2 inhibitors, these anti-diabetic agents could be used in patients with non-diabetic kidney disease." (PMID 33923115, 2021). "Despite an ability to reduce albuminuria, treatment with DPP-4 inhibitors has not been accompanied by beneficial changes in the clinical course of diabetic nephropathy." (PMID 29310647, 2018). "Of the globally marketed DPP-4 inhibitors, linagliptin is of particular interest for diabetic nephropathy as it is the only compound that is not predominantly excreted in the urine." (PMID 29491123, 2018). "Taken together, these findings suggest that both DPP-4 inhibitors and GLP-1RA could be attractive therapeutic options against diabetic nephropathy." (PMID 27483245, 2016).
diabetic nephropathy (continued). "Our major findings were that gemigliptin, a new DPP-4 inhibitor, had non-glucoregulatory tissue-protective effects on both diabetic nephropathy and cardiomyopathy." (PMID 26959365, 2016). "Interestingly, the administration of DPP-4 inhibitors has been shown to attenuate diabetic nephropathy in type 1 diabetic animal models independent of glucose-lowering." (PMID 27483245, 2016). "Experimental studies have suggested a renoprotective role of DPP-4 inhibitors in various models of chronic kidney disease (CKD), including diabetic nephropathy, which may be independent of lowering glucose levels." (PMID 28761658, 2017).
chronic kidney disease (73 papers, 2015 to 2025). Impairment of the renal function secondary to chronic kidney damage persisting for three or more months. "Awareness regarding the risk of pancreatitis linked to DPP-4 inhibitors was demonstrated by 76.4% of physicians, and 90.1% acknowledged their safe use in patients with chronic kidney disease (CKD)." (PMID 40734861, 2025). "Empagliflozin treatment is also associated with a lower risk of HF, all-cause mortality, and end-stage renal disease in comparison with dipeptidyl peptidase-4 (DPP-4) inhibitors in routine clinical practice in Japan, South Korea, and Taiwan." (PMID 36338417, 2022). "Analysis of comorbidities revealed a slightly higher prevalence of hyperlipidemia, chronic renal failure, and ischemic heart disease in the DPP-4 inhibitor group." (PMID 40869643, 2025). "Older age, chronic kidney disease (OR 0.52, 95% CI 0.41–0.66), and concurrent use of dipeptidyl peptidase 4 inhibitors (DPP4i) (OR 0.09, 95% CI 0.09–0.10) significantly reduced the likelihood of SGLT2i use." (PMID 40589143, 2025). "Dipeptidyl peptidase-4 (DPP-4) inhibitors are commonly used antidiabetic agents for patients with advanced-stage chronic kidney disease (CKD)." (PMID 35254430, 2022). "Further, based on in vivo chronic kidney disease models, DPP4 inhibitors were reported to enhance Ang1-7 production through ACE2 expression." (PMID 36685490, 2022). "The renoprotective effects of DPP-4 inhibitors on chronic kidney disease have been reported in several clinical trials, and recently reviewed by some researchers." (PMID 32084231, 2020). "Another hypoglycaemic drug class, dipeptidyl peptidase 4 inhibitors, has been approved for its use in patients with advanced chronic kidney disease, avoiding, in part, the need for insulinization in this group of DKD patients." (PMID 31212945, 2019). "Although the mechanism of the renoprotective effect of DPP-4 is not fully known, it has been suggested that DPP-4 inhibitors provide endothelial protection by reducing oxidative stress and inflammation in clinical studies performed among patients with chronic kidney disease." (PMID 35530894, 2022). "Other DPP-4 inhibitors may be used in the setting of chronic kidney disease with proper dose adjustment." (PMID 31366085, 2019). "Indeed, recent studies have highlighted the potential beneficial effects of DPP-4 inhibitors in chronic kidney disease." (PMID 29317794, 2017). "Glycoprotein DPP-4, which has been found in healthy individuals in two forms of circulating soluble and membrane-bound with a predominancy in proximal convoluted tubules, was also expressed in glomeruli as an adaptive mechanism in patients with chronic kidney disease." (PMID 35610696, 2022). "Dipeptidyl peptidase-4 (DPP-4) inhibitors, which can be used relatively safely in patients with chronic kidney disease (CKD), are also increasingly used." (PMID 35501824, 2022). "In addition to providing protective effects against tubular damage and slowing the progression of chronic kidney disease, it has been suggested that the renoprotective effects of DPP-4 inhibitors may be due to increased levels of GLP-141." (PMID 30333575, 2018). "On the other hand, real-world observational evidence has suggested that SGLT2-i use, compared with dipeptidyl peptidase-4 inhibitors use, may be associated with an even lower risk of hospitalizations due to genitourinary infections among patients with and without chronic kidney disease." (PMID 39458136, 2024). "Furthermore, the effects of SGLT2 inhibitors and DPP-4 inhibitors on serum uric acid (SUA) are known to increase during chronic kidney disease (CKD)." (PMID 36142907, 2022). "The effect of DPP4 inhibitors on oxidative stress in persons with TD2 and chronic kidney disease has been investigated in a randomised clinical trial (n = 45) comparing the effect of treatment with teneligliptin compared to sitagliptin." (PMID 34012064, 2021).
chronic kidney disease (continued). "We have reported that GLP-1R expression is enhanced by inhibition of GLP-1 degradation via dipeptidyl peptidase-4 (DPP-4) inhibition, and that GLP-1R activity is decreased in chronic kidney disease (CKD)." (PMID 31795376, 2019). "Avoid combining GLP-1 agonist with dipeptidyl peptidase 4 (DPP-4) inhibitors as there are no clear-cut data yet available that DPP inhibitors improve outcomes in cardiovascular disease or chronic kidney disease." (PMID 37834846, 2023). "Similarly, the adherence of DPP4 inhibitors in patients with chronic kidney disease (CKD) was significantly higher (OR [95% CI] of adherence for DPP4 inhibitors: 1.41 [1.25–1.59], p < 0.01) than pioglitazone, a well-established second-line therapy for T2DM patients with CKD." (PMID 35033161, 2022). "We examined the real-world comparative safety of sodium-glucose cotransporter-2 inhibitors (SGLT2i) vs. other newer anti-glycemic medications (dipeptidyl peptidase-4 inhibitors [DPP4i], glucagon-like peptide-1 receptor agonists [GLP1a]) in patients with and without chronic kidney disease (CKD)." (PMID 38993538, 2024). "Over the last decade, DPP-4 inhibitors have shown a steady uptake in prescription volume, and due to their preferable safety profiles they have been preferably used in T2DM patients with chronic kidney diseases and in those intolerant to adverse effects from other oral antidiabetics." (PMID 37891260, 2023). "CKD = chronic kidney disease; DPP-4 = dipeptidyl peptidase-4; GLP-1 RA = glucagon-like peptide-1 receptor agonist; SGLT-2 = sodium-glucose co-transporter-2." (PMID 30878037, 2019). "Additionally, DPP-4 inhibitors exert antiproteinuric effects, and SGLT-2 inhibitors, when used over a prolonged period, help prevent the progression of chronic kidney disease (CKD)." (PMID 41181754, 2025). "Experimental studies have shown that urinary dipeptidyl peptidase 4 (uDPP4), unlike serum DPP4 (sDPP4) activity, correlates with proteinuria, serum creatinine, and left ventricular (LV) hypertrophy in chronic kidney disease (CKD) models, suggesting a potential role for uDPP4 in CKD progression." (PMID 40604004, 2025). "Most DPP-4 inhibitors are eliminated renally and therefore require dose adjustment in CKD (chronic kidney disease), except linagliptin, which is mainly eliminated via the enterohepatic route, and can be used in patients with CKD without dose adjustment." (PMID 41012462, 2025). "Although the effects of dipeptidyl peptidase 4 (DPP-4) inhibitors beyond their hypoglycemic action have been reported, whether these inhibitors have renoprotective effects in nondiabetic chronic kidney disease (CKD) is unclear." (PMID 28118775, 2017).